FHL1 (four and a half LIM domains 1)
Diseases named in the same sentence as FHL1 in open-access papers (continued):
Sharing a sentence is not in itself a finding about the gene and the disease.
tumor (continued). "Thus, FHL1 is considered a tumor suppressor gene that acts downstream of v-Src and Cas to specifically inhibit anchorage-independent cell growth and migration." (PMID 32587768, 2020). "Upon phosphorylation, FHL1 translocates to the nucleus where it acts as a tumor promoter." (PMID 32587768, 2020). "Moreover, FHL1 is reported to inhibit tumor cell growth and migration by associating with diverse signals, such as TGF-β and ER, and therefore considered a tumor suppressor." (PMID 32587768, 2020). "According to these authors, due to its ability in inhibiting specific aspects of tumor cellular growth, FHL1 could have a tumor suppressor activity." (PMID 29454310, 2018). "Our findings showed that FHL1 overexpression inhibited tumor growth in both two cell lines." (PMID 26908444, 2016). "FHL1 is an important tumor-suppressor that is downregulated in multiple tumors by unknown mechanisms." (PMID 25272045, 2014). "Interestingly, Fhl1 is downregulated in many types of solid malignancies and it exhibits tumor suppressor activity." (PMID 20525254, 2010). "Since FHL-1 shares the C regulatory functions with factor H it can be proposed that it perhaps controls C activation within the microenvironment of tumour cells." (PMID 12402151, 2002). "The relatively high number of factor H and FHL-1 molecules bound to the tumour cells, approximately 104 and 5×104 per cell, respectively, is probably due to an abundancy of low affinity receptors, e.g. glycosaminoglycans or sialic acid-type polyanions on the cell surfaces." (PMID 12402151, 2002). "Thus, we confirmed that IMUP promotes tumor progression of PDAC by regulating FHL1 expression." (PMID 35142956, 2023). "Thus, we hypothesized that FHL1 may mediate the inhibition of tumor growth induced by IMUP depletion." (PMID 35142956, 2023). "Furthermore, phosphorylated FHL1-stimulated tumor cell growth appeared dependent on BCLAF1." (PMID 32587768, 2020). "Moreover, a recently published study found a significant association of FHL1 downregulation and its promoter methylation in OSCC cell lines and tumor samples, also suggesting that inactivation of the FHL1 in OSCCs is through DNA methylation of the promoter region." (PMID 29454310, 2018). "FHL1, a LIM-domain protein, and PITX2, a homeobox transcription factor, both function as tumor suppressors or oncogenes depending on the cellular context and are involved in regulating major signaling cascades such as MAPK, TGF-β, and WNT/β-catenin pathways." (PMID 40503897, 2025). "Consistent with the RNA-Seq data, validation of DEGs expression by qRT-PCR and GEPIA cohort showed that FHL1 and SLIT3 were down-regulated in LUAD patient tissues compared with non-tumor tissues." (PMID 36752296, 2023). "Meanwhile, aberrant low expression of FHL1 in CRC tissues was also confirmed by Western blot using adjacent normal and tumor tissue samples (P < 0.05)." (PMID 34335951, 2021). "FHL1 enhanced anchorage-independent growth of HCC cells and tumor growth in nude mice treated with paclitaxel." (PMID 32587768, 2020). "Here, the authors show that the LIM domain-containing proteins (for example, FHL1) induce inhibitory CDC25 phosphorylation resulting in radioresistance and that a specific peptide can increase tumour radiosensitivity by increasing CDC25 activity." (PMID 28094252, 2017). "OTUD1 may inhibit the proliferation, migration, and invasion of NSCLC cells by deubiquitinating and stabilizing the tumor suppressors KLF4 and FHL1." (PMID 41050073, 2025). "Interestingly, Fhl1 (Four and a Half LIM Domains 1; UniProt Q13642) suppresses tumor growth, yet the phosphorylated protein acts as a tumor promoter." (PMID 38193115, 2024). "FHL1 expression did not significantly differ with age, gender, tumor size, tumor location or distant metastasis (all P > 0.05)." (PMID 34335951, 2021).
tumor (continued). "FHL1 was identified functionally interacted with oestrogen receptors (ERs), Smad2/3/4, HIF-1, human T-cell leukemia virus type 1 Tax oncoprotein and ZO-1 in various cancer types, suggesting that its functions as either a tumor suppressor or oncoprotein." (PMID 26908444, 2016). "Two cell lines (U118 and U87) produced only factor H. This result showed that the production of factor H and FHL-1 is not a ubiquitous property of all tumour cells, but restricted to certain tumour cell types." (PMID 12402151, 2002). "FHL1 is a well known tumor-suppressor gene with no or relatively low expression in tumors." (PMID 25272045, 2014). "The relatively high proportion of FHL-1, as compared to factor H, in the SK-OV-3 and Caov-3 cell growth supernatants suggested that FHL-1 may have a role in the control of the alternative C pathway activation against tumour cells." (PMID 12402151, 2002). "In addition to the cell membrane regulators, it is possible that factor H, FHL-1 and soluble MCP may restrict C activation and prevent deposition of the terminal C components to the surfaces of tumour cells." (PMID 12402151, 2002). "Additionally, overexpression of FHL1 dramatically inhibited the volume and the weight of tumors from HN-13 and CAL-27 xenograft models by inducing cell differentiation, decreasing expression of Ki67, Cyclin D1 and promoting apoptosis of HN-13 xenograft tumor cells." (PMID 26908444, 2016). "Alternatively, OTUD1 may inhibit the proliferation, migration, and invasion of NSCLC cells by deubiquitinating and stabilizing the tumor suppressors KLF4 and FHL1, but the authors did not delve into the ubiquitination site of KLF4." (PMID 41050073, 2025). "They found that nonenzymatic tumor cell IDO1 activity increased expression of complement factor H (CFH) and its isoform, factor H like protein (FHL-1) in human GBM, resulting in increased intratumoral Tregs and myeloid-derived suppressor cells, accelerated tumor growth and poor survival." (PMID 37876966, 2023).
myopathies (37 papers, 2011 to 2025). "The increase in FHL1 in Pompe mouse muscle reflects another link to muscular disorders with reduced body myopathy (based on hemizygous FHL1 variants) as the most striking example." (PMID 37371072, 2023). "Mutation of Fhl1 is the causative factor of several X-linked hereditary myopathies that are collectively termed Fhl1-related myopathies." (PMID 36817606, 2023). "Over the past 10+ years, FHL1 has been identified as the causative gene mutated in at least six distinct myopathies affecting skeletal and cardiac muscles with a widely variable clinical manifestation in affected patients." (PMID 34745373, 2021). "Defects in the FHL1 gene are known to be linked to multiple human myopathies, but little is known of the functions and regulation of FHL1 in skeletal muscle." (PMID 33322515, 2020). "Mutations in the FHL1 gene have been reported to be associated with various human myopathies, including X-linked myopathy with postural muscle atrophy, reducing body myopathy, scapuloperoneal myopathy, and Emery–Dreifuss muscular dystrophy." (PMID 33322515, 2020). "Calsequestrin is a Ca2+-binding protein, which has been showed to be decreased in dystrophic mouse skeletal muscle, while mutation in the FHL1 gene is associated with myopathy." (PMID 31906061, 2019). "Since a number of thorough reviews on FHL-1 associated myopathies have been published prior to 2011, we will focus our discussion on new information, originating after 2011." (PMID 25961035, 2015). "Our data is the first report on Kv1.5 expression in myoblasts from patients with a myopathy associated with mutations in FHL1." (PMID 22053194, 2011). "In addition, FHL1 plays a relevant role in muscle tissue development and is implicated in some myopathies." (PMID 39519555, 2024). "Reducing body myopathy due to FHL1 mutations is an X-linked disorder, marked by the presence of intracytoplasmic inclusion bodies that contain a multitude of proteins, among which mutant FHL1 protein is the most represented." (PMID 37176163, 2023). "Mutations in the FHL1 gene are associated with various myopathies." (PMID 32587768, 2020). "Mutations and abnormal expression of MYBPC2 or LDB3 have been associated with myopathies and cardiopathies, which indicates that cytoskeletal proteins participate in the formation of pathological changes in FHL1 KO mice." (PMID 30083183, 2018). "Over 25 different FHL1 mutations have been identified in patients with decreasing body myopathy." (PMID 26908444, 2016). "Interestingly, disrupting FHL1 expression blocks muscle cell differentiation, and its mutation results in myopathy associated with protein aggregation." (PMID 27992858, 2016). "Although mutations in FHL-1 protein are commonly linked to the development of skeletal and cardiac myopathies, we are just beginning to unravel the molecular mechanisms underlying the pathogenesis of these myopathies." (PMID 25961035, 2015). "Twenty-seven mutations have been identified in the FHL1 gene that contribute to the development of six different myopathies, each of which present a combination of various protein aggregates, joint contractures, muscle atrophy/hypertrophy, and cardiovascular diseases." (PMID 24265776, 2013). "This could result in symptoms associated with some of the FHL1-induced myopathies, including decreased mobility, limb weakness, and joint contractures." (PMID 24265776, 2013). "The presence of intact FHL1C as occurring in XMPMA patients might contribute to the relative mild phenotype when compared to other FHL1 mutation-associated myopathies." (PMID 22053194, 2011). "Overexpression of FHL1 promoted the transformation of muscle fibers to the oxidative type, which, in the context of the myopathies evaluated in this study, supports fiber switching occurring in p. major." (PMID 40841884, 2025). "Neurological examination should be performed for syndromic HCM and myopathies (i.e., FHL1 with contractures)." (PMID 37685777, 2023).
myopathies (continued). "Mutations in the FHL1 gene cause many distinct heart and musculoskeletal diseases, which have been categorized into FHL1-related myopathies or FHL1opathies20." (PMID 37884534, 2023). "Comprehensive studies on FHL1-related muscle cell function have been performed in view of the critical roles of FHL1 in myopathies." (PMID 32587768, 2020). "FHL1 knockout in mice, on the other hand, increased skeletal muscle autophagic activity and induced myopathies with irregular structure and muscle fiber size, suggesting an important role of FHL1 in myogenesis and muscle integrity." (PMID 33322515, 2020). "Several studies have validated the importance of FHL1 in muscle development, myopathy, and cardiovascular diseases." (PMID 32587768, 2020). "In the past decade, accumulating findings on the functions of FHL1 have been documented, among which FHL1-related myopathies are the most comprehensively characterized." (PMID 32587768, 2020). "Loss of the FHL1 protein can cause muscle hypertrophy, reduced subcutaneous fat, rigid spine, short stature and further extends the phenotype of FHL1-related myopathies." (PMID 30083183, 2018). "This extended the phenotype of FHL1-related myopathies and should prompt future testing in undiagnosed patients who present with unexplained muscle hypertrophy, contractures and a rigid spine, particularly if the patient is male." (PMID 30083183, 2018). "In the context of myofibrillar myopathies, mitochondrial pathology has been reported in patients with mutations in filamin-C, myotilin, ZASP, FHL1, plectin, and desmin." (PMID 27393313, 2016). "Overexpression of FHL1 in mouse skeletal muscle promotes myocardial fusion and hypertrophy, observations with potential implications for human myopathy." (PMID 22053194, 2011). "Furthermore, FHL1 knockout mice develop age-dependent myopathy with myofibrillar/intermyofibrillar disorganization." (PMID 41408398, 2025). "Since FHL1 is highly expressed in skeletal muscle, an increasing number of studies have focused on the role of FHL1 in skeletal muscle integrity and myopathy, and several recent studies have demonstrated that FHL1 is a crucial regulator of skeletal myogenesis and muscle maintenance." (PMID 33322515, 2020). "Surprisingly, although the index patient showed a complete loss of FHL1 within the skeletal muscle no morphological signs of a myopathy were reported or detected during autopsy, respectively." (PMID 31293105, 2019). "FHL1-null mice develop age-dependent myopathy and increased autophagic activity." (PMID 30083183, 2018). "We hypothesize that abnormal expression or mutations of FHL1-binding partners (gamma-actin or non-muscle myosin IIB) participate in the pathogenesis of some FHL1-induced myopathies." (PMID 24265776, 2013). "Thus studying FHL1 protein interactions would provide a greater insight into its functional role in skeletal muscle development and the pathogenesis of CCF or other myopathies induced by FHL1." (PMID 24265776, 2013). "Furthermore, FHL1-null mice develop age-dependent myopathy and increased autophagic activity." (PMID 30083183, 2018). "Furthermore FHL1-null mice developed age-dependent myopathy and increased autophagic activity." (PMID 30083183, 2018). "As previously reported for members of a German family affected by a familiar reducing body myopathy, females carrying the C150R amino acid change in the FHL1 LIM2 domain showed various clinical manifestations and may be asymptomatic, reflecting different degrees of X-inactivation." (PMID 27443559, 2016). "In our microarray assays, CCNA1 expression was detectable at very low levels in healthy controls as well as in some other myopathies such as CAV3, DYSF and FHL1." (PMID 24019929, 2013).
myopathies (continued). "Since the functional properties of FHL1 are likely to be mediated by a diversity of interacting partners, the study of FHL1 protein interactions in skeletal muscle development may provide new insights into its functional role in CCF pathogenesis and other FHL1-induced myopathies." (PMID 24265776, 2013). "However, the Z-disc complex containing FHL1, gamma-actin, non-muscle myosin IIB, its functional capabilities in skeletal muscle development and its mechanism in CCF (or other myopathies) induced by FHL1 have not been delineated, and require further investigation." (PMID 24265776, 2013).
cancer (33 papers, 2002 to 2025). A tumor composed of atypical neoplastic, often pleomorphic cells that invade other tissues. "Gain- and loss-function studies found that FHL1 inhibits cancer cell growth, migration, and invasion." (PMID 39519555, 2024). "This review primarily focuses on the dual role and underlying mechanisms of action of FHL1 in human cancer progression and its clinical relevance." (PMID 32587768, 2020). "The FHL1 protein acted to inhibit the growth of cancer cells via arresting the cells at the G1/S and G2/M phases." (PMID 41439026, 2025). "The nine genes identified in our signature (Dhx9, Dusp12, Fhl1, Ifitm1, Ndufs1, Pja2, Slc1a3, Soga1, and Spon2) have each been investigated for their role in cancer." (PMID 38193115, 2024). "FHL1 can be silenced by miR-410 or EZH2 epigenetically and regulates cancer cell growth, and is associated with transcriptional machinery." (PMID 36752296, 2023). "Many studies have reported that FHL1 undergoes epigenetic regulation by promoter methylation in various cancers, and NPM1 plays an important role in epigenetic regulation." (PMID 35142956, 2023). "Among them, seven genes (FHL1, SELL, VIM, IGFBP7, TNFAIP3, LCP2, and SLC7AB) were associated with the cancer-immunity cycle." (PMID 35565437, 2022). "FHL1 is understood as a tumor repressor gene in various cancers and a possible target for cancer treatment." (PMID 36017148, 2022). "FHL1-dependent decrease in cancer cell growth is mediated by interactions with SMAD proteins, leading to a transforming growth factor (TGF)-like response." (PMID 32587768, 2020). "Here, we present an overview of the cellular function of FHL1 and discuss recent advances in understanding its role in cancer." (PMID 32587768, 2020). "Reports that some cancer tissues specifically upregulate FHL-1 expression, thereby evading immune surveillance, suggests a pronounced regulatory activity of the splice variant." (PMID 33178228, 2020). "Consistently, knockdown of FHL1 in vitro increased the sensitivity of cancer cells to ionizing radiation (IR)." (PMID 32587768, 2020). "Based on more recent findings over the last decade, FHL1 is proposed to play a dual role in cancer progression." (PMID 32587768, 2020). "CDC25C knockdown in cancer cells or CDC25C KO in MEFs greatly abrogated the ability of FHL1 knockdown by increasing the survival of the irradiated cells." (PMID 28094252, 2017). "FHL1 regulated G2/M arrest mainly through CDC25C because CDC25C knockdown in cancer cells or CDC25C KO in MEFs greatly abolished such effect." (PMID 28094252, 2017). "In a variety of cardiac disorders, FHL1 expression was also significantly up-regulated whereas its expression is down-regulated in certain cancers, suggesting its various physiological and pathological functions." (PMID 26908444, 2016). "Recent studies have shown that FHL1 also has important functions in tumorigenesis and cancer progression." (PMID 24952875, 2014). "To investigate candidate miRNAs that regulate FHL1 expression in cancer, we used 2 target prediction programs, TargetScan and miRanda." (PMID 25272045, 2014). "The expression of FHL1 in the carcinoma tissues was less on average than the expression in the paracancerous (normal) tissues (P = 0.009, n = 55)." (PMID 25272045, 2014). "It is important to highlight that considering the significant differences observed in the expressions of Fhl1 between different tumors, Fhl1 is advised as a prognostic marker and could be a potential target for cancer therapy research including NHL." (PMID 41011134, 2025). "Over the past decade, Fhl1 has been found to play a dual role in cancer progression." (PMID 40424254, 2025). "In fact, FHL1 is suppressed by promoter methylation in many cancers." (PMID 35142956, 2023). "To date, there have been no GCT cases linked with FHL-1 mutations and no malignant disease has been found associated with EDMD." (PMID 37309342, 2023).